TFB2M (transcription factor B2, mitochondrial)
Description:
S-adenosyl-L-methionine-dependent rRNA methyltransferase which may methylate two specific adjacent adenosines in the loop of a conserved hairpin near the 3'-end of 12S mitochondrial rRNA (Probable). Component of the mitochondrial transcription initiation complex, composed at least of TFB2M, TFAM and POLRMT that is required for basal transcription of mitochondrial DNA. In this complex, TFAM recruits POLRMT to a specific promoter whereas TFB2M induces structural changes in POLRMT to enable promoter opening and trapping of the DNA non-template strand. Stimulates transcription independently of the methyltransferase activity.
Synonyms: h-mtTFB; h-mtTFB2; hTFB2M; mtTFB2; FLJ23182; FLJ22661; Hkp1
Tractability: PROTAC: ubiquitination databases record sites on it; its protein half-life has been measured.
Target class: Enzyme; Transferase
Gene: Protein-coding gene on chromosome 1 (246,540,561 to 246,566,261, reverse strand). Ensembl gene ENSG00000162851.
Subcellular location: Mitochondrion
Subcellular location (Human Protein Atlas): Mitochondria
Pathways (Reactome):
Gene expression (Transcription): Mitochondrial transcription initiation
Organelle biogenesis and maintenance: Transcriptional activation of mitochondrial biogenesis
Gene Ontology:
Molecular function: mitochondrial transcription factor activity; RNA binding; rRNA (adenine-N6,N6-)-dimethyltransferase activity; rRNA (adenine-N6-)-methyltransferase activity
Biological process: mitochondrial transcription; transcription initiation at mitochondrial promoter; rRNA methylation; rRNA modification
Cellular component: mitochondrial matrix; mitochondrial nucleoid; mitochondrion
Genetic constraint (gnomAD): Loss-of-function variants: 31 observed, 36.2 expected, observed/expected ratio (o/e) 0.86, 90% interval 0.64 to 1.16. The upper end of that interval is the gene's LOEUF score, 1.16, which puts it in group 5 of 6, group 1 being the genes least tolerant of losing a copy. Missense variants: 448 observed, 461.48 expected, observed/expected ratio (o/e) 0.97, 90% interval 0.9 to 1.05. Synonymous variants: 172 observed, 169.78 expected, observed/expected ratio (o/e) 1.01, 90% interval 0.89 to 1.15.
Homologues: Orthologues: chimpanzee TFB2M (99% identical), macaque TFB2M (85% identical), rat Tfb2m (54% identical), pig TFB2M (53% identical), dog TFB2M (53% identical), mouse Tfb2m (53% identical), tropical clawed frog tfb2m (38% identical), zebrafish tfb2m (35% identical). Paralogues in human: DIMT1 (15% identical), TFB1M (15% identical).
Diseases named in the same sentence as TFB2M in open-access papers:
TFB2M is named in the same sentence as 25 diseases in open-access papers, as found by Europe PMC text mining. Sharing a sentence is not in itself a finding about the gene and the disease. The quoted sentences say what the papers report.
ovarian carcinoma (3 papers, 2024). A malignant neoplasm originating from the surface ovarian epithelium. "TFB2M overexpression is also associated with increased extracellular mtDNA and elevated IL-6 expression in ovarian cancer cells and promote the infiltration of M2 macrophages through the cytoplasmic mtDNA/TLR9/NF-κB/IL-6 pathway." (PMID 38589371, 2024). "Specifically, the overexpression of TFB2M in ovarian cancer is negatively correlated with the survival rate of ovarian cancer patients and moderately positively correlated with tumor-associated macrophage (TAM) infiltration." (PMID 38589371, 2024). "Mitochondrial transcription factor B2 (TFB2M), responsible for the mitochondrial DNA (mtDNA) transcription and compacting, is expressed in ovarian cancer patients, and is associated with poor prognosis, immunosuppressive TME and macrophage polarization." (PMID 38397187, 2024).
glioblastoma (2 papers, 2018 to 2024). The most malignant astrocytic tumor (WHO grade IV). "In the present study, we showed that TFAM and other mitochondrial transcription factors (TFB1M and TFB2M) may be targets of melatonin in glioblastoma cells." (PMID 29747444, 2018). "In summary, our results suggest that increased generation of melatonin-induced intracellular ROS in U87MG glioblastoma cells may be an effect of melatonin on the expression of TFAM and other mitochondrial transcription factors (TFB1M and TFB2M), leading to mitochondrial disruption." (PMID 29747444, 2018).
Sepsis (2 papers, 2020 to 2024). Sepsis is defined as life-threatening organ dysfunction caused by a dysregulated host response to infection. "Despite increased extramitochondrial TFAM both intramitochondrial TFAM abundance and the functionally important protein interaction with TFB2M are decreased in PBMCs from sepsis patients." (PMID 33273525, 2020). "Aside from mechanistic considerations, it is intriguing to speculate that the extent and duration of the apparent intracellular TFAM maldistribution might represent a prognostic biomarker, since TFAM/TFB2M protein interactions strongly correlated with the SOFA score of our sepsis patients." (PMID 33273525, 2020).
bacterial sepsis (1 paper, 2025). "In bacterial sepsis, a reduced number of protein interactions between TFAM and TFB2M measured in PBMCs was associated with inefficient mitochondrial recovery and increased mortality in sepsis." (PMID 40458415, 2025).
chronic kidney disease (1 paper, 2022). Impairment of the renal function secondary to chronic kidney damage persisting for three or more months. "Additionally, up-regulated TFB2M was examined in chronic kidney disease compared with normal kidneys." (PMID 36246620, 2022).
Cirrhosis (1 paper, 2023). A chronic disorder of the liver in which liver tissue becomes scarred and is partially replaced by regenerative nodules and fibrotic tissue resulting in loss of liver function. "Analyses of expression data in GSE14323 showed increased expression of ZNF281 in HCC compared with normal and cirrhosis liver tissues but decreased expression of PGC-1α, TFAM, TFB1M, and TFB2M." (PMID 37880213, 2023).
COVID-19 (1 paper, 2025). A disease caused by infection with severe acute respiratory syndrome coronavirus 2. "Here, our study introduces a new method to evaluate the interaction between the mitochondrial proteins TFAM and TFB2M, overcoming the limitations of current mRNA and protein biomarkers in COVID-19." (PMID 40458415, 2025). "Specifically, we shed light on the promising role of mitochondrial biogenesis assessed via the interaction between TFAM and TFB2M in peripheral blood of critical COVID-19 patients." (PMID 40458415, 2025). "Of note, the protein interaction between TFAM and TFB2M is just one promising example among many significant protein interactions involved in severe infections like critical COVID-19." (PMID 40458415, 2025). "Thus, the objective of this study is to investigate different mRNA transcripts related to mitochondrial repair and quality control including the protein interaction between TFAM and TFB2M targeting mitochondrial biogenesis, as predictors for clinical outcome in patients with critical COVID-19." (PMID 40458415, 2025). "A further promising candidate to assess mitochondrial repair in patients suffering from COVID-19 is the interaction between mitochondrial transcription factor A (TFAM) and mitochondrial transcription factor B2 (TFB2M)." (PMID 40458415, 2025).
hepatocellular carcinoma (1 paper, 2024). A malignant tumor that arises from hepatocytes. "In hepatocellular carcinoma (HCC), the overexpression of TFB2M is associated with abnormal activation of the ROS-Akt-NF-κB signaling pathway, promoting tumor growth and metastasis." (PMID 38589371, 2024).
IgA nephropathy (1 paper, 2022). "Especially, DDX27, RCL1, and TFB2M were significantly linked to most immune cell populations and immune checkpoints, indicating that above characteristic RBPs might participate in modulating immune cell infiltrations during IgA nephropathy progression." (PMID 36246620, 2022). "Among characteristic RBPs, TFB2M negatively correlated to several pyroptosis-relevant genes, indicating that TFB2M might modulate pyroptosis pathway during IgA nephropathy." (PMID 36246620, 2022). "After integration of above machine learning algorithms, we finally determined TFB2M, DDX27, and RCL1 as characteristic RBPs of IgA nephropathy." (PMID 36246620, 2022). "Through integration of three machine learning approaches (LASSO, SVM-RFE, random forest), we finally determined three characteristic RBPs of IgA nephropathy: DDX27, RCL1, and TFB2M." (PMID 36246620, 2022). "Compared with normal specimens, TFB2M, DDX27, and RCL1 expressions were significantly down-regulated in IgA nephropathy." (PMID 36246620, 2022). "However, no studies have reported the roles of DDX27, RCL1, and TFB2M in IgA nephropathy." (PMID 36246620, 2022).
malignant astrocytoma (1 paper, 2016). "In malignant astrocytoma cells, decreased mtDNA copy numbers correlate with increased levels of mitochondrial POLG and mitochondrial transcription factors (TFAM, and TFB1M, and TFB2M)." (PMID 27486856, 2016).
melanoma (1 paper, 2024). A malignant, usually aggressive tumor composed of atypical, neoplastic melanocytes. "The multivariate Cox OS model, the 50–cross-validated relaxed LASSO analysis, as well as the stepwise procedure, identified a combination of 3 genes — HIST1H2BL, MGEA5, and TFB2M — as our melanoma risk score." (PMID 38319712, 2024).
oral cancer (1 paper, 2021). "Similarly, 24 and 72 h POMx treatment inhibits mRNA and protein expressions for mitochondrial biogenesis of gene expression (TFB2M, TFAM, POLRMT, and TUFM) in oral cancer cells." (PMID 34356350, 2021).
osteosarcoma (1 paper, 2022). A usually aggressive malignant bone-forming mesenchymal neoplasm, predominantly affecting adolescents and young adults. "To this end, we evaluated the viability of the human osteosarcoma 143B cells after inactivating TFAM, POLRMT, TFB2M, POLG, POLG2, or SSBP1 with CRISPR-Cas9." (PMID 35883613, 2022).
tumor (7 papers, 2015 to 2024). "Although the precise regulation of TFB2M in tumor progression has not been extensively studied, some research has demonstrated the potential value of modulating TFB2M expression for the treatment of cancer." (PMID 38589371, 2024). "Moreover, the key mtDNA transcription factors POLRMT, TFAM, TFB1M and TFB2M were down-regulated in the GBM50 and GBM3 tumours." (PMID 30208958, 2018).
cancer (3 papers, 2008 to 2024). A tumor composed of atypical neoplastic, often pleomorphic cells that invade other tissues. "While there is limited specific information available on the role of TFB2M in cancer, dysregulation of mitochondrial transcription factors, including TFB2M, has been implicated in various types of cancer." (PMID 38589371, 2024). "Moreover, dysregulation of mitochondrial transcription factors, such as POLRMT, TFAM, TFB2M, and MTERFs, has been implicated in cancer development and progression." (PMID 38589371, 2024).
TFB2M also shares sentences with these, for which no sentence is quoted: adenocarcinoma (2 papers); lung carcinoma (2); anemia (1); autistic spectrum disorder (1); brain tumor (1); congenital cataracts (1); developmental delay (1); Hematological Disease (1); lung adenocarcinoma (1); neuropathy (1).